EGFR (epidermal growth factor receptor)
Diseases named in the same sentence as EGFR in open-access papers (continued):
Sharing a sentence is not in itself a finding about the gene and the disease.
metastatic colorectal cancer (continued). "For example, the epidermal growth factor receptor (EGFR) is a major therapeutic target in metastatic colorectal cancer." (PMID 27756306, 2016). "Resistance to epidermal growth factor receptor (EGFR) targeted monoclonal antibody therapy represents a clinical challenge in patients suffered from RAS wild-type (WT) metastatic colorectal cancer (mCRC)." (PMID 27825133, 2016). "The combination of epidermal growth factor receptor inhibitor with fluorouracil, leucovorin, and irinotecan was originally designed for the treatment of metastatic colorectal cancer." (PMID 27091477, 2016). "Panitumumab, a fully human monoclonal antibody targeting the epidermal growth factor receptor (EGFR), is effective as monotherapy and in combination with chemotherapy for treatment of patients with metastatic colorectal cancer (mCRC)." (PMID 27736842, 2016). "Panitumumab and cetuximab target the epidermal growth factor receptor for the treatment of metastatic colorectal cancer." (PMID 27658254, 2016). "Patients with metastatic colorectal cancer (mCRC) harboring wild-type KRAS benefit from epidermal growth factor receptor (EGFR)-targeted therapy." (PMID 26657506, 2016). "The anti EGFR-antibodies cetuximab and panitumumab represent well-established treatments for metastatic colorectal cancer (CRC), the third most prevalent cancer entity and fourth most common cause of cancer-related death around the world." (PMID 27485514, 2016). "For instance, Panitumumab and Cetuximab are both monoclonal antibodies targeting the epidermal growth factor receptor, and used for treating EGFR-expressing metastatic colorectal cancers." (PMID 27526853, 2016). "This single-arm phase II study investigated the EGFR monoclonal antibody necitumumab plus modified FOLFOX6 (mFOLFOX6) in first-line treatment of locally advanced or metastatic colorectal cancer (mCRC)." (PMID 26766738, 2016). "The antibody cetuximab, targeting epidermal growth factor receptor (EGFR), is used to treat metastatic colorectal cancer (mCRC)." (PMID 26719345, 2016). "Approximately 5-10% of metastatic colorectal cancers harbor a BRAF-V600E mutation, which is correlated with resistance to EGFR-targeted therapies and worse clinical outcome." (PMID 26160848, 2015). "Despite the demonstrated benefits of anti-EGFR/VEGF targeted therapies in metastatic colorectal cancer (mCRC), many patients initially respond, but then show evidence of disease progression." (PMID 26107817, 2015). "In 2014 the European Medicines Agency included exon 2, 3 and 4 KRAS and NRAS testing for the selection of metastatic colorectal cancer (mCRC) patients eligible for the therapy with anti-EGFR monoclonal antibodies." (PMID 26335936, 2015). "The mutation in KRAS exon 2 is a validated biomarker of resistance to anti-epidermal growth factor receptor (EGFR) therapy in metastatic colorectal cancer (mCRC)." (PMID 25886136, 2015). "Anti-epidermal growth factor receptor therapy with the monoclonal antibodies cetuximab and panitumumab is the main targeted treatment to combine with standard chemotherapy for metastatic colorectal cancer." (PMID 26318427, 2015). "In the treatment of metastatic colorectal cancer, monoclonal antibodies against epidermal growth factor receptor (EGFR), such as cetuximab and panitumumab, have been used in clinical practice since 2004." (PMID 26691448, 2015). "Anti-EGFR monoclonal antibodies (mAb) such as cetuximab, panitumumab are one kind of efficacious targeted drugs in treatment of metastatic colorectal cancer (mCRC)." (PMID 26363448, 2015). "An example is the incorporation in standard care of the mutation status of KRAS and NRAS, which is decisive in starting epidermal growth factor receptor (EGFR)-targeted therapy on metastatic colorectal cancer patients." (PMID 26047774, 2015). "It is well documented that EGFR signaling is the most important pathway in treating metastatic colorectal cancer." (PMID 25896895, 2015).
metastatic colorectal cancer (continued). "A recent meta-analysis reported that PIK3CA exon 20 mutations are associated with a significantly shorter DFS in KRAS wild-type metastatic colorectal cancer patients treated with anti-EGFR antibody cetuximab." (PMID 25980437, 2015). "KRAS genotyping is mandatory in metastatic colorectal cancer treatment prior to undertaking antiepidermal growth factor receptor (EGFR) monoclonal antibody therapy." (PMID 25983749, 2015). "The RAS (K-RAS and N-RAS) molecular testing represented a further step towards a more accurate selection of metastatic colorectal cancer patients clinically candidates to receive treatment with anti-EGFR monoclonal antibodies." (PMID 25943333, 2015). "Gefitinib (Iressa, AstraZeneca), a small reversible EGFR inhibitor, and IMC-C225 (Erbitux, ImClone Systems), an inhibitory anti-EGFR monoclonal antibody, have been approved for non small-cell lung and metastatic colorectal cancer treatment, respectively." (PMID 26079945, 2015). "New therapeutic options for metastatic colorectal cancer (mCRC) patients, including therapy with cetuximab and panitumumab antibodies targeting epidermal growth factor receptor (EGFR), have improved patient survival." (PMID 26497852, 2015). "Acquired resistance to epidermal growth factor receptor (EGFR) targeted antibodies represents a clinical challenge in the treatment of gastrointestinal tumors such as metastatic colorectal cancer, but its molecular mechanisms are incompletely understood." (PMID 26059438, 2015). "There were significant differences in survival among GPS scores of 0, 1 and 2 in patients with metastatic colorectal cancers treated with bevacizumab or anti-EGFR therapy." (PMID 25924723, 2015). "EGFR inhibition-targeted therapy is a new biologic therapy for the treatment of metastatic colorectal cancer which is also adenocarcinoma of intestinal type." (PMID 25297496, 2014). "Monoclonal antibodies targeting the Epidermal Growth Factor Receptor (EGFR), such as cetuximab and panitumumab, have evolved to important therapeutic options in metastatic colorectal cancer (CRC)." (PMID 24676216, 2014). "Cetuximab, a chimeric monoclonal antibody developed for targeting the Epidermal Growth Factor Receptor (EGFR), has been intensively used to treat cancer patients with metastatic colorectal cancer and head and neck cancer." (PMID 25438047, 2014). "The human epidermal growth factor receptor (EGFR) is an important therapeutic target in patients with metastatic colorectal cancer and anti-EGFR antibodies cetuximab and panitumumab have been approved for the treatment of such patients." (PMID 24609222, 2014). "As a result, there has been a substantial development of molecular therapies targeting EGFR and subsequent approval of anti-EGFR mAbs, such as cetuximab and panitumumab, for the treatment of patients with metastatic colorectal cancer." (PMID 24609222, 2014). "These efforts have, for instance, revealed that the expression level of the miR-31-3p allows the identification of patients with wild-type KRAS metastatic colorectal cancer responding to anti-EGFR therapy." (PMID 25243170, 2014). "Since anti-EGFR antibodies have been shown to improve overall survival in metastatic colorectal cancer." (PMID 25003232, 2014). "For example, analysis of the metastatic colorectal cancer xenopatients cohort allowed to identify HER2 as a predictor of resistance to anti-EGFR antibodies and as a predictor of response to combinatorial therapies against HER2 and EGFR in this tumor setting." (PMID 23992330, 2014). "In comparison, panitumumab is a fully humanized IgG2 monoclonal antibody, which also targets EGFR and is approved for use in metastatic colorectal cancer." (PMID 25277503, 2014). "Recently, any activating mutations in the KRAS gene has been proved to be predictor of response to epidermal growth factor receptor-targeted therapies, such as cetuximab and panitumumab, for patients with metastatic colorectal cancer." (PMID 25267307, 2014).
metastatic colorectal cancer (continued). "Recents studies have demonstrated that mutations in the KRAS gene negatively predict the response to EGFR-targeted therapies in patients with metastatic colorectal cancer." (PMID 25267307, 2014). "Similar results were obtained for Cetuximab, a monoclonal antibody that blocks EGFR and is approved for metastatic colorectal cancer." (PMID 25053989, 2014). "Three of the four studies reporting on metastatic colorectal cancer involved only patients treated with anti-EGFR therapy 19,23,26." (PMID 24890702, 2014). "As the response rate (RR) to anti-EGFR MoAbs remains as low as 10–20 % in patients with metastatic colorectal cancer (mCRC), several studies have been performed to identify markers predicting the efficacy of these agents." (PMID 24500024, 2014). "KRAS activating mutations are widely recognised as predictors of resistance to the treatment with anti-EGFR monoclonal antibodies (moAbs) in metastatic colorectal cancer (mCRC) patients." (PMID 25361007, 2014). "Epidermal growth factor receptor monoclonal antibody was approved for treatment of metastatic colorectal cancer patients carrying KRAS wild type DNA." (PMID 23874486, 2013). "In July 2008, cetuximab, a monoclonal antibody against epidermal growth factor receptor (EGFR), was approved in Japan for clinical use against chemotherapy-refractory metastatic colorectal cancer (mCRC)." (PMID 24137455, 2013). "Advances in the treatment of metastatic colorectal cancer (mCRC) include the development of new antitumoral agents, including epidermal growth factor receptor-targeted monoclonal antibodies (EGFR-mAbs) and tyrosine kinase inhibitors, and the use of biomarkers." (PMID 24179521, 2013). "It has been suggested that in order for metastatic colorectal cancer patients to receive a response for treatment with monoclonal antibodies targeting EGFR (panitumumab and cetuximab), the BRAF gene needs to be present as wild-type." (PMID 24298448, 2013). "Cetuximab (Cmab), a chimeric monoclonal antibody for targeting the epidermal growth factor receptor, has become one of the standard treatments for metastatic colorectal cancer (mCRC)." (PMID 23599782, 2013). "Following the treatment guidelines for metastatic colorectal cancers expressing wild-type K-ras gene, anti-EGFR therapy with panitumumab was administered." (PMID 23426888, 2013). "Cetuximab (Erbitux, C225) is an anti-EGFR (epidermal growth factor receptor) antibody used for the treatment of metastatic colorectal cancer and head and neck cancer." (PMID 24028754, 2013). "Two such mAbs, panitumumab and cetuximab, are active in metastatic colorectal cancer, but the clinical evidence shows that approximately 10% of patients achieve an objective tumor response to anti-EGFR mAbs." (PMID 23441167, 2013). "The anti–EGFR monoclonal antibody is effective in prolonging survival in patients with metastatic colorectal cancer after failure of conventional chemotherapy." (PMID 23441167, 2013). "Anti-epidermal growth factor receptor (EGFR) monoclonal antibodies are approved for the treatment of metastatic colorectal cancer (CRC)." (PMID 22534075, 2012). "EMP1 is involved in the EGFR signaling pathway with an important role in cell proliferation and epithelial cell differentiation and it is considered important in metastatic colorectal cancer." (PMID 23119007, 2012). "Panitumumab is a fully human monoclonal antibody targeting the EGFR that significantly improves progression-free survival when added to chemotherapy in patients with metastatic colorectal cancer who have wild-type (WT) KRAS tumours." (PMID 23020584, 2012). "The employment of anti-epidermal growth factor receptor (EGFR) antibodies represents a backbone of the therapeutic options for the treatment of metastatic colorectal cancer (mCRC)." (PMID 22911782, 2012).
metastatic colorectal cancer (continued). "The two “biologic” therapeutic strategies that have demonstrated activity in metastatic colorectal cancer target the epidermal growth factor receptor (EGFR) and vascular endothelial growth factor (VEGF) both in first and second-line of therapy." (PMID 22701615, 2012). "One of the most successfully approach in the treatment of metastatic colorectal cancer (mCRC) is the inhibition of the Epidermal Growth Factor Receptor (EGFR) pathway by antibodies (cetuximab and panitumumab)." (PMID 23316197, 2012). "Cetuximab is a chimeric (mouse/human) IgG1monoclonal antibody directed against EGFR that is administered by intravenous infusion for treatment of metastatic colorectal cancer and head and neck cancer." (PMID 22139134, 2012). "The association of KRAS gene mutation and response to therapy was first reported in patients with metastatic colorectal cancer, who were treated with anti-epidermal growth factor receptor (EGFR) agents." (PMID 23202889, 2012). "In metastatic colorectal cancer (mCRC) a selected group of patients with wild-type KRAS respond to antibodies against the epidermal growth factor receptor (EGFR)." (PMID 23173730, 2012). "The epidermal growth factor receptor monoclonal antibody cetuximab has proven activity in metastatic colorectal cancer." (PMID 22439666, 2012). "Epidermal growth factor receptor gene copy number (EGFR GCN) has been heavily investigated as a potential predictive biomarker for the treatment of metastatic colorectal cancer (mCRC) with anti-EGFR monoclonal antibodies (MAbs)." (PMID 22897982, 2012). "The epidermal growth factor receptor (EGFR) mAB cetuximab has proven activity in metastatic colorectal cancer." (PMID 22439666, 2012). "In metastatic colorectal cancer, monoclonal antibodies directed against EGFR, currently cetuximab and panitumumab, have been implemented in clinical practice for the last eight years." (PMID 23226389, 2012). "During the recent past years, a targeted therapy with monoclonal antibodies (cetuximab and panitumumab), blocking the EGFR-driven cell proliferation signals, has been introduced into the therapy of metastatic colorectal cancer." (PMID 22931052, 2012). "Cetuximab has been proven to be effective in irinotecan-resistant metastatic colorectal cancer expressing EGFR, detected by immunohistochemistry (IHC), with response rates ranging from 8.8% when used as monotherapy to 22.9% when combined with irinotecan." (PMID 22139134, 2012). "Anti-EGFR monoclonal antibodies have shown efficacy in the treatment of metastatic colorectal cancer (mCRC)." (PMID 23171437, 2012). "The epidermal growth factor receptor-targeted monoclonal antibody cetuximab (Erbitux) was recently introduced for the treatment of metastatic colorectal cancer." (PMID 21712828, 2011). "Panitumumab is a fully human antibody against the epidermal growth factor receptor that is indicated for the treatment of metastatic colorectal cancer (mCRC) after disease progression on standard chemotherapy." (PMID 22070868, 2011). "For metastatic colorectal cancer (mCRC) treatment by EGFR-targeted drugs is one of few therapeutic alternatives." (PMID 22272141, 2011). "The currently followed practice is to offer treatment with anti EGFR therapy to patients with metastatic colorectal cancer harboring wild type KRAS only." (PMID 24212832, 2011). "Findings reported in the literature support additional testing of BRAF, PTEN and PIK3CA before anti-EGFR treatment in metastatic colorectal cancer." (PMID 22272141, 2011). "The aim of our study was then to verify a possible correlation between EGFR gene promoter methylation and clinical outcome in metastatic colorectal cancer patients receiving chemotherapy with irinotecan and cetuximab." (PMID 21559018, 2011). "The primary aim of our study was to verify a possible correlation between EGFR gene promoter methylation and clinical outcome in metastatic colorectal cancer patients receiving chemotherapy with irinotecan and cetuximab." (PMID 21559018, 2011).
metastatic colorectal cancer (continued). "Selection of patients for epidermal growth factor receptor targeted monoclonal antibodies (MoAbs) based on tumour KRAS analysis is a major step towards tailored treatment in metastatic colorectal cancer." (PMID 21439039, 2011). "Of metastatic colorectal cancers that are found to be KRas wild type at codons 12/13, 5% to 15% can harbor BRAF mutations and show resistance to anti-EGFR therapy." (PMID 21403829, 2011). "KRAS mutational analysis is the standard of care prior to initiation of treatments targeting the epidermal growth factor receptor (EGFR) in patients with metastatic colorectal cancer." (PMID 21110880, 2010). "Two anti-epidermal growth factor receptor (EGFR) monoclonal antibodies (MoAbs) have been approved in Canada for the treatment of metastatic colorectal cancer (mCRC) – cetuximab, a mouse-human chimeric MoAb, and panitumumab, a fully human MoAb." (PMID 20680105, 2010). "For example, the epidermal growth factor receptor (EGFR) has become an important target for treatment of metastatic colorectal cancer (mCRC), specifically with the monoclonal antibodies (mAbs) cetuximab and panitumumab." (PMID 20959826, 2010). "Since 2004, the clinical impact of monoclonal antibodies (mAbs) targeting the epidermal growth factor receptor (EGFR) on patients with metastatic colorectal cancer (MCRC) has been clearly established." (PMID 21139621, 2010). "Inhibitors of epidermal growth factor receptor (EGFR), including the monoclonal antibodies panitumumab and cetuximab, have recently emerged as treatment options for metastatic colorectal cancer (mCRC)." (PMID 20398393, 2010). "Several studies indicate greater benefit from a Cetuximab therapy for EGFR expressing metastatic colorectal cancer patients with KRAS wild type." (PMID 21197450, 2010). "Combination of targeted biological agents such as anti-epidermal growth factor receptor (EGFR) with FOLFOX have been reported to enhance the efficacy against EGFR-expressing metastatic colorectal cancer." (PMID 20051959, 2010). "The anti-EGFR monoclonal antibody cetuximab is used in metastatic colorectal cancer (CRC), and predicting responsive patients garners great interest, due to the high cost of therapy." (PMID 19439077, 2009). "Newer agents such as Bevacizumab have successfully targeted the tyrosine kinase receptor epidermal growth factor receptor in metastatic colorectal cancer." (PMID 19118499, 2009). "KRAS codons 12 and 13 activating mutations are widely recognised as predictors of resistance to the treatment with anti-EGFR monoclonal antibodies (moAbs) in metastatic colorectal cancer (mCRC) patients." (PMID 19603018, 2009). "To further corroborate our observations, we selected a different neoplastic condition from the recent literature: metastatic colorectal cancer treated with the EGFR inhibitor cetuximab (Erbitux®)." (PMID 19229342, 2009). "Cetuximab (Erbitux®), a monoclonal antibody targeting EGFR, is currently used in EGFR-expressing metastatic colorectal cancer (mCRC) in combination with cytotoxic chemotherapy (irinotecan), after failure of a previous irinotecan-based regimen." (PMID 18544172, 2008). "Cetuximab, a monoclonal antibody targeting Epidermal Growth Factor Receptor (EGFR), is currently used in metastatic colorectal cancer (mCRC), but predictive factors for therapeutic response are lacking." (PMID 18544172, 2008). "The role of additional agents, such as anti-EGFR compounds or angiogenesis inhibitors should be defined in the therapeutic strategy of the metastatic colorectal cancers, in combination with oral fluoropyrimmidine containing regimen." (PMID 16404362, 2006). "This phase II study examined the efficacy and safety of erlotinib, an oral EGFR TK inhibitor, in patients with metastatic colorectal cancer." (PMID 16570047, 2006).